SYT9 (synaptotagmin 9)
Description:
May be involved in Ca(2+)-dependent exocytosis of secretory vesicles through Ca(2+) and phospholipid binding to the C2 domain or may serve as Ca(2+) sensors in the process of vesicular trafficking and exocytosis.
Tractability: Antibody: its Gene Ontology location is reachable by antibodies, with high confidence; UniProt predicts a signal peptide or a membrane-spanning region. PROTAC: ubiquitination databases record sites on it.
Gene: Protein-coding gene on chromosome 11 (7,238,778 to 7,469,043, forward strand). Ensembl gene ENSG00000170743.
Subcellular location: Cytoplasmic vesicle, secretory vesicle, synaptic vesicle membrane
Pathways (Reactome):
Vesicle-mediated transport: Cargo recognition for clathrin-mediated endocytosis; Clathrin-mediated endocytosis
Neuronal System: Neurexins and neuroligins
Gene Ontology:
Molecular function: protein binding; calcium ion sensor activity; calcium-dependent phospholipid binding; SNARE binding; identical protein binding; phosphatidylinositol-4,5-bisphosphate binding; phosphatidylserine binding
Biological process: chemical synaptic transmission; positive regulation of vesicle fusion; regulation of calcium ion-dependent exocytosis; vesicle-mediated transport; calcium-dependent activation of synaptic vesicle fusion
Cellular component: clathrin-coated endocytic vesicle membrane; dense core granule; exocytic vesicle; plasma membrane; hippocampal mossy fiber to CA3 synapse; membrane; synaptic vesicle membrane
Genetic constraint (gnomAD): Loss-of-function variants: 22 observed, 47.86 expected, observed/expected ratio (o/e) 0.46, 90% interval 0.33 to 0.66. The upper end of that interval is the gene's LOEUF score, 0.66, which puts it in group 2 of 6, group 1 being the genes least tolerant of losing a copy. Missense variants: 577 observed, 623.14 expected, observed/expected ratio (o/e) 0.93, 90% interval 0.86 to 0.99. Synonymous variants: 265 observed, 246.48 expected, observed/expected ratio (o/e) 1.08, 90% interval 0.97 to 1.19.
Homologues: Orthologues: chimpanzee SYT9 (99% identical), macaque SYT9 (99% identical), rabbit SYT9 (98% identical), dog SYT9 (98% identical), mouse Syt9 (98% identical), rat Syt9 (97% identical), guinea pig SYT9 (97% identical), pig SYT9 (96% identical), zebrafish syt9b (75% identical), zebrafish syt9a (73% identical), tropical clawed frog syt9 (63% identical). Paralogues in human: SYT10 (59% identical), SYT6 (59% identical), SYT3 (53% identical), SYT1 (31% identical), SYT2 (31% identical), SYT7 (30% identical), SYT17 (29% identical), SYT5 (29% identical), SYT11 (27% identical), SYT4 (26% identical), SYT12 (24% identical), SYT15 (24% identical), and 19 more.
Diseases named in the same sentence as SYT9 in open-access papers:
SYT9 is named in the same sentence as 11 diseases in open-access papers, as found by Europe PMC text mining. Sharing a sentence is not in itself a finding about the gene and the disease. The quoted sentences say what the papers report.
Alzheimer disease (1 paper, 2022). A progressive, neurodegenerative disease characterized by loss of function and death of nerve cells in several areas of the brain leading to loss of cognitive function such as memory and language. "Gene-based analyses implicated AGXT2 and CALN1 for VL, while analyses of protein-protein interactions implicated synaptic proteins previously associated with Alzheimer disease biology, SYT9 and NRXN1 for VSTM; ZFAND5, GRIK2, and ZC3H18 for VL; and PRLHR for paragraph recall." (PMID 35974141, 2022).
cardiomyopathies (1 paper, 2023). "In particular, Males Only DMRs selected by machine learning feature selection were able to distinguish CHD from non-CHD samples and frequently mapped to genes associated with CHDs or cardiomyopathies, including FUNDC1, ETV5, SYT9, CAMTA1, GRIA4, and IGF1R." (PMID 37803336, 2023).
gastric cancer (1 paper, 2021). A primary or metastatic malignant neoplasm involving the stomach. "1.The expressions of SYT4, SYT9 and SYT14 were up-regulated in gastric cancer (GC)." (PMID 34229539, 2021).
type 1 diabetes (1 paper, 2020). "Cells treated with molecules mimicking type 1 diabetes lost granules with synaptotagmin-7, while granules with synaptotagmin-9 were lost in cells treated with fatty acids to imitate type 2 diabetes." (PMID 33164744, 2020).
cancer (1 paper, 2021). A tumor composed of atypical neoplastic, often pleomorphic cells that invade other tissues. "According to increasing evidence on the correlations between immune cell infiltration and prognosis in cancer, we utilized the TIMER database to evaluate the association between the expressions of SYT4, SYT9, and SYT14 and immune cell infiltration." (PMID 34229539, 2021).
tumor (1 paper, 2020). "Some genes in this module were connected by processes proposed to be involved in tumor progression, such as DOC2A, CGN (Cingulin), PARD6B, NEDD4L, and SYT9 which belonged to the KEGG pathway, tight junction (TJ) (hsa04530), and GEO term, cell junctions (GO:0030054)." (PMID 32605588, 2020).
SYT9 also shares sentences with these, for which no sentence is quoted: basophilic leukemia (1 paper); neuroblastoma (1); periodontitis (1); prostate carcinoma (1); type 2 diabetes (1).